CCDC175 (coiled-coil domain containing 175)
Synonyms: C14orf38; c14_5395
Tractability: PROTAC: ubiquitination databases record sites on it.
Gene: Protein-coding gene on chromosome 14 (59,504,539 to 59,576,812, reverse strand). Ensembl gene ENSG00000151838.
Subcellular location (Human Protein Atlas): Nucleoplasm; Cytosol; Nucleoli
Genetic constraint (gnomAD): Loss-of-function variants: 30 observed, 32.95 expected, observed/expected ratio (o/e) 0.91, 90% interval 0.68 to 1.24. The upper end of that interval is the gene's LOEUF score, 1.24, which puts it in group 5 of 6, group 1 being the genes least tolerant of losing a copy. Missense variants: 356 observed, 348.33 expected, observed/expected ratio (o/e) 1.02, 90% interval 0.94 to 1.12. Synonymous variants: 130 observed, 125.18 expected, observed/expected ratio (o/e) 1.04, 90% interval 0.9 to 1.2.
Homologues: Orthologues: chimpanzee CCDC175 (95% identical), macaque CCDC175 (91% identical), pig CCDC175 (66% identical), dog CCDC175 (65% identical), rabbit CCDC175 (63% identical), rat Ccdc175 (52% identical), mouse Ccdc175 (50% identical).
Diseases named in the same sentence as CCDC175 in open-access papers:
CCDC175 is named in the same sentence as 2 diseases in open-access papers, as found by Europe PMC text mining. Sharing a sentence is not in itself a finding about the gene and the disease.
CCDC175 shares sentences with these, for which no sentence is quoted: Behçet’s Disease (1 paper); Vogt-Koyanagi-Harada Syndrome (1).